CCR4 (C-C motif chemokine receptor 4)
Diseases named in the same sentence as CCR4 in open-access papers (continued):
Sharing a sentence is not in itself a finding about the gene and the disease.
herpesvirus infection (1 paper, 2023). "Our data establish that mRNA deadenylation by host CCR4‐NOT is critical for productive HCMV replication and define a new mechanism whereby herpesvirus infection subverts cellular mRNA metabolism to remodel the gene expression landscape of the infected cell." (PMID 37846490, 2023).
Hypercholesterolemia (1 paper, 2025). An increased concentration of cholesterol in the blood. "Another interesting finding is that CCR4 deficiency markedly upregulated Th1 cell responses in peripheral lymphoid tissues as well as in atherosclerotic lesions under hypercholesterolemia." (PMID 40608058, 2025). "To determine whether CCR4 deficiency affects the suppressive function of Tregs in hypercholesterolemia, we performed an in vitro suppression assay." (PMID 40608058, 2025). "Similar results were obtained for normocholesterolemic wild-type mice, suggesting that the expansion of Tregs and effector memory T cells in Ccr4-/-Apoe-/- mice is independent of hypercholesterolemia." (PMID 40608058, 2025).
infertile (1 paper, 2020). "The identification of BTG4 mutations in infertile women supports our hypothesis that BTG4/CCR4-NOT-induced mRNA deadenylation is involved in the regulation of maternal mRNA stability during human MZT." (PMID 33004802, 2020).
IPEX syndrome (1 paper, 2021). "Interestingly, Treg express an affinity towards skin-homing through CCR4, CCR6, and cutaneous lymphocyte-associated antigen (CLA), a similar mechanism as seen in IPEX syndrome, caused by a Treg defect." (PMID 34080085, 2021).
ischemia (1 paper, 2019). A hypoperfusion of the BLOOD through an organ or tissue caused by a PATHOLOGIC CONSTRICTION or obstruction of its BLOOD VESSELS, or an absence of BLOOD CIRCULATION. "As a receptor of CKLF1, CCR4 showed no obvious change among rats in sham, ischemia or IMM-H004 treatment groups." (PMID 30987181, 2019).
latent infection (1 paper, 2022). "CD27 and CD26 were among the markers which best discriminated fast and slow responders, consistently with prior studies associating CD27 and CCR4 expression in Mtb-specific CD4+ T-cells with active TB compared to latent infection." (PMID 35392094, 2022).
leukoplakia (1 paper, 2015). A white patch or plaque on a mucous membrane that cannot be characterized clinically or pathologically as any other disease. "Although CCR4+ T cells were rare in normal mucosa and in leukoplakia lesions (data not shown), CXCR3+ and CCR5+ T cells abundantly infiltrated the subepithelial stroma of leukoplakia." (PMID 26242181, 2015).
lipodystrophy (1 paper, 2019). A congenital or acquired disorder characterized by abnormal loss or redistribution of the adipose tissue in the body. "We showed that mice lacking subunits of the CCR4–NOT complex had similar adipocyte abnormalities, including development of lipodystrophy and cold sensitivity (and this study)." (PMID 31652943, 2019).
liver failure (1 paper, 2014). A liver disease characterized by the liver losing or has lost all of its function. "Together, these data indicate that CCR2 and CCR4 signaling are required for microglia activation and subsequent production of the proinflammatory cytokines IL-1β and IL-6 following AOM-induced liver failure." (PMID 25012628, 2014).
lupus nephritis (1 paper, 2018). Glomerulonephritis in the context of systemic lupus erythematosus. "Furthermore, the frequency of CD4+CD45RO+CCR4+ lymphocytes correlated strongly with both ESR and CRP pointing to the potential proinflammatory role of these cells in lupus nephritis." (PMID 29670615, 2018).
male reproductive system diseases (1 paper, 2023). "Utilizing the CTD database, we demonstrated that the five hub genes (CD300LB, CMKLR1, CCR4, B3GALT5, and CTSK) significantly affected male reproductive system diseases." (PMID 37152990, 2023).
medulloblastoma (1 paper, 2015). A malignant, invasive embryonal neoplasm arising from the cerebellum. "When hAT-MSCs were co-cultured with medulloblastoma-BTICs, the expression levels of CCR4, CCR5, CCR7, XCR1, CXCR1, CXCR4, PDGFR-bb, KDR and TEK were increased, while the levels of CX3CR1, IL1R, IL6R, IL8R, IGF1R and CD44 were decreased (p<0.05)." (PMID 26076490, 2015).
metastatic melanoma (1 paper, 2017). A melanoma that has spread from its primary site to another anatomic site. "IHC staining indicated that metastatic melanomas (LNM and MBM) exhibited significantly (p < 0.05) higher expression of CCR4 than paired PRMs." (PMID 28415693, 2017).
morbid obesity (1 paper, 2023). An excess of body weight, normally defined as an individual with a body mass index greater than 35 or a body weight greater than one hundred percent of ideal body weight. "Given that little is known regarding CCR4 axes and leukocyte-endothelium interactions in human morbid obesity, we sought also to study their functional significance in an ex vivo model of dysfunctional endothelium using the parallel-plate flow chamber system." (PMID 37124725, 2023). "The aim of this study was to investigate the role of chemokine receptor CCR4 and its ligands CCL17 and CCL22 in human morbid obesity." (PMID 37124725, 2023).
myeloid leukemia (1 paper, 2024). A clonal proliferation of myeloid cells and their precursors in the bone marrow, peripheral blood, and spleen. "Here, we uncovered CNOT3, a subunit of the CCR4-NOT complex, as an essential modulator of translation in myeloid leukemia." (PMID 38491013, 2024).
myocarditis (1 paper, 2012). Myocarditis is a condition that is characterized by inflammation of the heart muscle (myocardium). "CXCL9 mRNA expression directly correlated with the intensity of myocarditis, as well as with mRNA expression of CXCR3, CCR4, CCR5, CCR7, CCR8 and their ligands." (PMID 23150742, 2012).
nasal polyps (1 paper, 2014). "In contrast, 9 out of 11 samples showed both CCR4 and CXCR3 expression of T cell in non-asthmatic nasal polyps." (PMID 25361058, 2014).
nephritis (1 paper, 2021). Inflammation of renal tissue. "Although the roles of CCR6 and CXCR3 in the recruitment of Tregs into the kidney have already been established in similar antibody-mediated nephritis models, CCR4 in Tregs during the late phase has not been investigated." (PMID 32917984, 2021).
Oral leukoplakia (1 paper, 2015). A thickened white patch on the oral mucosa that cannot be rubbed off. "Intriguingly, the infiltrated CD4+ T cells in oral leukoplakia consisted of CXCR3+ and CCR5+ Th1 cells, a major IFN-producing cell type, and CCR4+ Th2 cells were rare in the lesion." (PMID 26242181, 2015).
pancreatitis (1 paper, 2019). Inflammation of the pancreas. "CCR4+ DCs and CCR4+ Tregs cooperate to promote resistance to CVB5-induced pancreatitis." (PMID 31611578, 2019). "Consequently, CVB5 infection of CCR4−/− mice aggravated the pancreatitis, as the pancreas presented more intense inflammatory infiltrates, edema and cell necrosis." (PMID 31611578, 2019). "To investigate whether CCR4 is important for the resistance of mice to CVB5 infection, we analyzed virus-induced pancreatitis in CCR4−/− mice." (PMID 31611578, 2019). "Consequently, CCR4−/− mice had reduced IFN-γ-producing T cells in the pancreas and lymph nodes and were more susceptible to CVB5-induced pancreatitis." (PMID 31611578, 2019). "This correlated with higher virus titers in CCR4−/− mice at the same time point, showing that CCR4 plays a significant role in conferring resistance to CVB5-induced pancreatitis." (PMID 31611578, 2019). "Collectively, the data show that CCR4+ DCs are responsible for the polarization of T cells towards a Th1 profile and confer resistance to CVB5-induced pancreatitis." (PMID 31611578, 2019). "The present data reveal a previously unknown role for CCR4 in coordinating immune cell migration to CVB-infected tissues and in controlling subsequent pancreatitis." (PMID 31611578, 2019). "Tregs were also induced or recruited to the PLN after CVB5 infection, and CCR4+ Tregs, but not CCR4− Tregs, were responsible for regulating T lymphocyte activation, which correlated with increased resistance to pancreatitis." (PMID 31611578, 2019). "Consequently, CCR4−/− mice presented decreased IFN-γ-producing CD4+ and CD8+ T cells, an increased viral load and more severe pancreatitis." (PMID 31611578, 2019). "By adoptive transfer of cells, we demonstrated that CCR4+ DCs are, at least in part, responsible for inducing CD4+ and CD8+ T cells-mediated IFN-γ production and for controlling the pancreatic injury, although CCR4− DCs may also play a role in the impairment of pancreatitis development." (PMID 31611578, 2019).
pituitary tumor (1 paper, 2024). A benign or malignant neoplasm affecting the pituitary gland. "Once activated, TAMs secrete CCL17, a chemokine that further fuels the invasive and metastatic potential of pituitary tumors, which engages the CCL17/C-C chemokine receptor type 4 (CCR4)/mTORC1 axis, thereby enhancing the tumor’s capacity for invasion and metastasis." (PMID 39456135, 2024).
primary progressive multiple sclerosis (1 paper, 2024). A multiple sclerosis that is characterized by steady worsening of neurologic functioning, without any distinct relapses or periods of remission. "However, CCR5+, CXCR3+, CCR6+ and CCR4+ cells within the CD4+ CD45RA− memory T-cell pool of the CSF of OCR-treated people with primary progressive multiple sclerosis were all depleted for CD20dim T cells, which was not the case for the CD8+ memory T-cell pool." (PMID 38385000, 2024).
psychosis (1 paper, 2020). "Further studies are needed to characterize the relevance of high circulating CCL22 levels or enhanced CCR4 signaling for CNS function, as well as for the altered cyto/chemokine networks in psychotic disorders." (PMID 32179746, 2020). "Earlier cross-sectional studies suggest a role of CCR4 signaling in psychosis." (PMID 32179746, 2020). "Our results do not support the over-active microglia hypothesis of psychosis, but indicate altered CCR4 immune signaling in early psychosis with behavioral correlates possibly mediated through cross-talk between chemokine networks and dysfunctional or a decreased number of glial cells." (PMID 32179746, 2020).
pulmonary arterial hypertension (1 paper, 2025). Pulmonary arterial hypertension (PAH) is a group of diseases characterized by mean pulmonary artery pressure >20 mmHg and elevated pulmonary arterial resistance leading to right heart failure. "In contrast, endothelial cells largely express several other chemokine receptors including CCR4, CCR5, CCR6, CXCR2, CXCR4, and CXCR5, and CXCR4, which plays a key role in pulmonary arterial hypertension (PAH) through an autocrine signaling mechanism." (PMID 40859641, 2025).
sarcoma (1 paper, 2022). A usually aggressive malignant neoplasm of the soft tissue or bone. "LINC00461 was inversely correlated with the survival of mice-bearing GBM and it was stabilized by the interaction between HDAC6 and RNA-binding proteins (RBPs) such as carbon catabolite repression—negative on TATA-less (CCR4-NOT) core exoribonuclease subunit 6 and fused in sarcoma." (PMID 35109908, 2022).
skin reaction (1 paper, 2015). "An anti-CCR4 monoclonal antibody, mogamulizumab (Poteligeo®) is commercially available in Japan and has a 50% response rate as a single agent in phase two studies with manageable toxicities, including skin reactions." (PMID 26610571, 2015).
skin tumor (1 paper, 2021). "In the present study, the frequency of CCR4+ cells in the skin tumor was increased in CCL17 TG mice as had been expected." (PMID 33670758, 2021). "As expected, the frequency of CCR4+ cells was increased in the skin tumors of CCL17 TG mice." (PMID 33670758, 2021).
Skin ulcer (1 paper, 2025). A discontinuity of the skin exhibiting complete loss of the epidermis and often portions of the dermis and even subcutaneous fat. "Similarly, CL recovered patients displayed increased TCM and diminished TEM and TTE CD4+CCR4+ and CD8+CCR4+ cells compared with patients with skin ulcers." (PMID 40277930, 2025).
squamous cell carcinoma of the lung (1 paper, 2023). "Patients with squamous cell carcinoma of the lung have higher levels of CCR4 expression in these cells, which is a predictor of survival and relapse." (PMID 37259456, 2023).
Stevens-Johnson syndrome (1 paper, 2022). Stevens-Johnson syndrome is a limited form of toxic epidermal necrolysis characterized by destruction and detachment of the skin epithelium and mucous membranes involving less than 10% of the body surface area. "Clinical trials of the anti-CCR4 antibody Mogamulizumab revealed the depletion of Treg cells in a subset of patients, coupled with extreme infiltration of T cells into the skin, resulting in Steven Johnson Syndrome (OMIM#608579)." (PMID 36268024, 2022).
tauopathy (1 paper, 2022). Neurodegenerative disorders involving deposition of abnormal tau protein isoforms (tau proteins) in neurons and glial cells in the brain. "Loss-of-function mutations in the ccr-4 and panl-2 genes of C. elegans increased the tauopathy phenotype, but loss of parn-2 reduced it." (PMID 35203497, 2022). "The enhanced tauopathy phenotype induced by loss of ccr-4 was alleviated by the loss of sut-2 and, contrarily, overexpression of sut-2 aggravated it even in the absence of parn-2." (PMID 35203497, 2022).
toxic epidermal necrolysis (1 paper, 2015). Toxic epidermal necrolysis (TEN) is an acute and severe skin disease with clinical and histological features characterized by the destruction and detachment of the skin epithelium and mucous membranes. "However, the anti-CCR4 mAb therapy induces several serious adverse effects, including Stevens–Johnson syndrome/toxic epidermal necrolysis, when normal CCR4+ Tregs are attacked." (PMID 26289727, 2015).
type 2 diabetes (1 paper, 2016). "In addition, CCR4 and CCR6 are more expressed in type 2 diabetes patients than in non-diabetic persons." (PMID 27869712, 2016).
urothelial carcinoma (1 paper, 2022). A malignant neoplasm derived from the transitional epithelium of the urinary tract (urinary bladder, ureter, urethra, or renal pelvis). "Our previous studies showed that regulatory T cell recruitment in canine urothelial carcinoma is caused by BRAFV595E mutation-driven CCL17/CCR4 pathway." (PMID 35027594, 2022).
Zinc deficiency (1 paper, 2025). A deficiency of the essential metal Zinc; an essential cofactor for many enzymes. "Here we show that sod1 mRNA and protein levels are reduced in response to zinc deficiency and that this regulation occurs in a manner that is dependent on the Caf1 and Ccr4 deadenylases of the CCR4-NOT complex." (PMID 39761853, 2025).
tumor (487 papers, 2007 to 2026). "In a previous study, CCR4 expression on more than 10% of tumor cells was shown to be associated with cutaneous involvement and to serve as an independent prognostic factor for all clinical subtypes of ATL." (PMID 40833211, 2025). "Previous research has shown that CCR4 and its ligands were associated with increased tumor recurrence and impaired OS in patients with GC." (PMID 38169378, 2024). "Considering the absolute decrease in the number of immune cells, B lymphocytes were most affected by the genetic loss of CCR4 (CCR4−/−: 2534 ± 809 CD19+ cells per 1 × 105 tumor cells vs. WT: 6287 ± 2426 CD19+ cells per 1 × 105 tumor cells; n = 9, p = 0.1616)." (PMID 37371612, 2023). "The methods for detecting macrophages (flow cytometry and immunohistochemistry) revealed the same trends with regard to the effects of a loss of CCR4, but they showed different proportions of macrophages in the tumor." (PMID 37371612, 2023). "Macrophages showed the second-largest CCR4-associated decline (CCR4−/−: 5180 ± 1524 F4/80+ cells per 1 × 105 tumor cells vs. WT: 7563 ± 1524 F4/80+ cells per 1 × 105 tumor cells; n = 9, p = 0.0127), with a mean absolute reduction of 2383 ± 2155 (35%)." (PMID 37371612, 2023). "Upregulated CCR4 expression has been observed in several types of cancers that associate with tumor growth, invasion, migration and even metastasis serving them as a critical target in various cancers including HCC." (PMID 37081509, 2023). "Nevertheless, the genetic loss of CCR4 led to a trend of reduced tumor-associated B-cell infiltration." (PMID 37371612, 2023). "Both CCL22 and CCL17, which are produced by tumor cells, tumor-associated macrophages, and dendritic cells, establish a concentration gradient around the tumor mass and attract CCR4+ Tregs to maintain immunological homeostasis in the tumor vicinity." (PMID 35222362, 2022). "In prostate cancer patients, CCR4+ Treg cells are found abundant in the tumor tissue and associate with poor prognosis." (PMID 35359918, 2022). "Here, we evaluated the association of CCR4 expression in cytotoxic T-lymphocytes (CTLs) with antigen and cytokine stimulations and kinase inhibition using cytomegalovirus antigen instead of tumor antigen." (PMID 36522365, 2022). "The distribution pattern of CCR4 in tumor-associated CD4+CD25+CD127- Treg populations in healthy donor and tumor patients was determined using a comparative t-SNE method based on multi-color flow cytometry data." (PMID 35222362, 2022). "In this study, cytomegalovirus (CMV) antigen was used instead of tumor antigen to evaluate the association between antigen stimulation and CCR4 expression." (PMID 36522365, 2022). "CCL22 and CCL17 are released by tumor cells and tumor-associated macrophages, attracting CCR4+ Tregs to the tumor site." (PMID 35222362, 2022). "Despite the importance of CCR4 in Treg tumor invasion, there is very little information on its transcriptional regulation in tumor-associated Treg cells." (PMID 35222362, 2022). "Tumor-infiltrating Foxp3+ Tregs and CCR4+ cells were increased in cases with BRAFV595E mutation in comparison to that in cases with wild-type BRAF." (PMID 35131860, 2022). "CCR4 is the major trafficking receptors for Treg cells and has been implicated in their recruitment into the tumor microenvironment." (PMID 34885241, 2021). "In a previous study using flow cytometry, surface CCR4 expression was mildly increased in tumor cells with mutated CCR4 genes, compared with tumor cells with wild type CCR4 genes." (PMID 33022137, 2021). "They exert an anti-cancer effect by causing the infiltration of TIL into the tumor, a process dependent on CCR4 on these cells." (PMID 33182504, 2020). "In vitro or in vivo mogamulizumab treatment selectively depleted CCR4+ Tregs and is associated with increased levels of tumor-antigen–specific T cells." (PMID 31801624, 2019).